IL6 (interleukin 6)
Diseases named in the same sentence as IL6 in open-access papers (continued):
Sharing a sentence is not in itself a finding about the gene and the disease.
colitis (continued). "Various colitis symptoms in mice, including body weight, thymus index, spleen index, IL-6, TNF-α, IL-1β, IL-10, and IgA, were restored with 100 mg/kg PSPRS and 300 mg/kg PSPRS administration." (PMID 38611336, 2024). "Formononetin can reduce the expression of IL-6 to alleviate colitis symptoms in mice and inhibit JAK2/STAT3 signaling pathway transduction to protect against cerebral ischemia reperfusion injury." (PMID 39318778, 2024). "For example, in a murine model of colitis-associated CRC, obstructing IL-6 signal transmission resulted in a reduction in tumor burden." (PMID 38612842, 2024). "After DSS-induced colitis we detected statistically significant increases in IL-22 and IL-18 concentration and insignificant but clearly visible trend in increase of IL-6 and IL-12p40." (PMID 39354587, 2024). "Mononuclear phagocytes and epithelial cells in the intestine can drive inflammatory cytokines, including IL-1β, TNF-a, and IL-6, which are involved in the occurrence and progression of colitis." (PMID 39458282, 2024). "Resolvin D1 (RvD1), a lipoxygenase (LOX) metabolite derived from DHA, has been shown to attenuate DSS-induced colitis by reducing the production of IL-6." (PMID 38672464, 2024). "The IL-6 levels in the colitis mouse model serum were significantly increased after 7 days of DSS treatment." (PMID 38504172, 2024). "As expected, RT-qPCR assay demonstrated that NGR1 treatment significantly reduced the mRNA levels of pro-inflammatory mediators COX-2, iNOS, and IL-6 in colitis mice." (PMID 38491161, 2024). "Cinnamic acid administration at doses of 25 and 50 mg/kg resulted in reduced levels of TNF-α and IL-6 in mice with DSS-induced colitis." (PMID 38732594, 2024). "The use of Magnolia officinalis bark extract (MBE) formed by both magnolol and honokiol prevented weight loss and suppressed the activation of the proinflammatory cytokine IL6 in DSS-induced colitis." (PMID 39494333, 2024). "We also observed increased levels of inflammatory cytokines TNF-α, IL-1β, and IL-6 in two colitis groups." (PMID 39118149, 2024). "The overexpression of the pro-inflammatory cytokine IL-6 in the colon indicated the increased sensitivity of EpCAM+/− mice to DSS-induced colitis compared to WT mice." (PMID 39188786, 2024). "Pro-inflammatory factors such as IL-6 and IL-1β are the cytokines that mediate the pathogenesis of colitis." (PMID 39473926, 2024). "THZ2 rescued the up-expression of COX2 and IL-6 in DSS-induced colitis and AOM/DSS-induced colitis-associated colorectal cancer." (PMID 38540292, 2024). "Indigo Naturalis (IN) notably improved colitis in mice by enhancing colon tissue structure, reducing pro-inflammatory cytokines (IL-6, IL-8, TNF-a), and increasing anti-inflammatory cytokine IL-10." (PMID 39411430, 2024). "The levels of IL-1β, TNF-α and IL-6 in the colitis tissues of β6-KO mice were lower than those of WT mice." (PMID 37223685, 2023). "Extract of Terminalia catappa containing phenolic acids, especially ellagic acid, a compound present also in CE, reduced the colonic expression of IL-6 in murine models of colitis." (PMID 37049797, 2023). "In our study, we observed that DSS-induced colitis was characterized by excessive inflammatory indicators, such as the upregulation of proinflammatory cytokines (IL-17, IL-6, IL-1β) in the colon and prevailing Th17/Treg cells in the MLNs." (PMID 37143672, 2023). "Pistacia lentiscus extract, containing an abundance of phenolic compounds, including those found in CE, namely caffeoylquinic acid and kaempferol glucosides, also decreased the level of IL-6 in experimental colitis." (PMID 37049797, 2023). "Previous reports have identified inflammatory cytokines such as IL-17, TNF-α, IL-23, and IL-6 as key players in the development of colitis." (PMID 37836692, 2023). "In our study, IL-1β, TNF-α, IL-6, and IL-17A contents within the colon increased after CR infection, conforming to prior research regarding CR-induced colitis." (PMID 37111225, 2023).
colitis (continued). "It is quite conceivable that IL-6 can play both a pro-inflammatory and anti-inflammatory role during the colitis progress depending on the mouse models." (PMID 36457188, 2023). "Here, increased levels of pro-tumorigenic cytokines (IL1β, IL-6, and MIP2) in animal models of colitis and animal models of CAC are associated with upregulated MLCK expression." (PMID 38002302, 2023). "Melanoma patients receiving anti-PD1 therapy demonstrated an increase in Th-1-mediated IL-6 production which led to severe colitis." (PMID 36769093, 2023). "Accordingly, we found that integrin β6 deficiency remarkably decreased the release of pro-inflammatory cytokines including TNF-α, IL-6 and IL-1β in the intestinal tissues of colitis." (PMID 37223685, 2023). "It has been reported that IL-6 levels increased in DSS colitis models in the acute phase of the disease and persisted during the chronic phase." (PMID 36792680, 2023). "PS attenuated the severity of colitis by reducing IL-2 and IL-6 and shifted the IM composition toward a healthier profile, increasing the concentration of Bifidobacterium and reducing the concentration of harmful bacteria in the gut." (PMID 37190329, 2023). "Excessive oxidative stress and abnormal production of proinflammatory cytokines are associated with colitis pathogenesis with the aberrant release of proinflammatory cytokines, including TNF-α, IFN-γ, IL-6, IL-8, IL-12, and IL-17." (PMID 36829894, 2023). "We found that the relative mRNA expression of Rfx1 and M1 macrophage–related genes Il6, Tnf, and Il1b were significantly increased in the colon tissue of mice with colitis compared with the control group." (PMID 37733446, 2023). "Elevated expression of Il6, Tnfa, and Il23a genes in whole lung tissue was seen in TCRδ-/- mice with colitis, with only the Tnfa gene being mildly elevated in the corresponding C57BL/6 mice." (PMID 37063825, 2023). "In an experimental colitis model, the administration of a mixture of heat-inactivated probiotics downregulated IL-6, IL-23, STAT3, and p-STAT3 expression in colonic tissues of colitic rats." (PMID 37894114, 2023). "To characterize the anti-inflammatory therapeutic potential of PR1P in TNBS-induced colitis, we quantified plasma levels of the pro-inflammatory mediators IL-1β, IL-6 and TNF-α on Day 7 following necropsy." (PMID 37187742, 2023). "It was also reported that the levels of TNF-α and IL-6 were altered in the serum of mice with early-stage colitis induced by one week of DSS administration." (PMID 36900589, 2023). "Odoribacter splanchnicus was shown to be useful in treating colitis and colorectal cancer by stimulating IL-6 and IL-1 production and Th17 cell expansion." (PMID 37260707, 2023). "In accordance, we found increased expression of IL-1 and IL-6 as well as pNF-kBs536 and pStat3y705 in Cldn2KO mice recovering from colitis." (PMID 37815870, 2023). "TNF, IL1B, and IL6 were increased in Il17b-/- mice compared with WT in colitis in both protein and mRNA levels." (PMID 36814913, 2023). "In fact, estrogens seem to modulate colitis severity in these models, and even cytokine expression, such as IL-6, is dependent on the sex of the animal." (PMID 37047397, 2023). "It is proved that oral TDNPs can reduce proinflammatory cytokines (TNF-α, IL-6 and IL-1β), upregulate antioxidant gene HO-1 to relieve colitis in mice and accelerate colitis regression." (PMID 37033644, 2023). "Previously, similar results reported that B. breve CCFM683 reduced colon inflammation by increasing colon length and reducing TNF-α, IL-1β and IL-6 expression in the colons of DSS-induced colitis mice." (PMID 36986118, 2023). "The therapeutic potential of IL-6 signaling blockade for CD, anti-IL-6R monoclonal antibody (mAb), was introduced to various murine models of colitis." (PMID 38137450, 2023). "The area under curve (AUC) of CRP + D-D + α2-MG for predicting distal colitis MES3 was 0.85, and the AUC of IL-6+ GSP+ α1-MG predicted extensive colitis MES3 can reach 0.82." (PMID 37457023, 2023).
colitis (continued). "The rectal administration of lactate reduced the early production of IL-6 in a murine model of colitis." (PMID 36769093, 2023). "Exposure to IS also caused colitis in mice: it shortened colon and increased colonic myeloperoxidase, TNF-α, and IL-6 expression and NF-κB+CD11c+ cell (dendritic and macrophage cells) number, resulting in colonic inflammation." (PMID 36926604, 2023). "The mLN cells in DSS colitis showed increased mRNA and protein levels of IL-1β, IL-6, IL-12, and IL-23, which were considerably increased by additional treatment with FimH." (PMID 38077339, 2023). "Quercetin can inhibit pro-inflammatory factor generation, such as IL-17, TNF-α, or IL-6, while promoting IL-10 production during CR-induced colitis." (PMID 37111225, 2023). "The inflammatory cytokines including TNF-α, IL-1β, IL-6, and IL-10 were higher in colitis mice than those in control mice (P < 0.01)." (PMID 36768559, 2023). "Turmeric-derived exosome-like nanoparticles suppressed the expression of pro-inflammatory cytokines, such as TNF-α, IL-6, and IL-1β, promoted the levels of antioxidant genes, particularly HO-1 by inactivating NF-κB pathway, and alleviated colitis." (PMID 37653406, 2023). "A shift from the inflammatory to regulatory immune phenotype of macrophages contributes to the alleviation of colitis by enhancing M2 polarization, restraining IL-6 production in M1 macrophages, and changing the gut homeostasis." (PMID 37813835, 2023). "While IL-1β blockade reduced ICI colitis severity in mice, IL-6 inhibition improved tumor response to ICI and suppressed irAE symptoms in preclinical models, and is being pursued as an approach to alleviate irAEs in patients." (PMID 36622383, 2023). "Apart from the involvement of neutrophils, there are other shared characteristics of DSS and ICI-related colitis, such as the elevation of IL-1β or IL-6." (PMID 37511839, 2023). "We observed an increase in IL-6 in AIRminSS mice (both mRNA expression and protein synthesis), indicating its importance in the colitis phenotype of those animals." (PMID 36792680, 2023). "As previously reported, the mRNA levels of inflammatory cytokines, Il6 (the gene encoding interleukin 6 (IL-6), Il17a, Tnf (the gene encoding tumor necrosis factor α), and Il1b, were increased in the colon of Vdr(+/−) mice with DSS-induced colitis." (PMID 36834927, 2023). "Ameliorated colitis symptoms, improved the intestinal barrier integrity, decreased the levels of IL-6, TNF-α." (PMID 37485519, 2023). "Consistently, the protein levels of inflammatory cytokines TNF-α, IFN-γ, IL-1β, and IL-6 in the serum of MKO colitis mice were increased." (PMID 36635421, 2023). "We also found that Olfm4 deletion leads to an enhanced immune response and inflammation in the progression of colitis, characterized by enhanced expression of complement Il-1β, Il-6, and Mcp-1 and activation of the NF-κB pathway." (PMID 37151883, 2023). "STAT3 plays a critical role in colitis pathology, and its activation is mediated by multiple cytokines such as IL-6." (PMID 37432218, 2023). "PA/CCMTS-P showed excellent anti-inflammatory effects both in vitro and in vivo, which obviously reduced the secretion of TNF-α, IL-6, IL-1β, and IL-18 after LPS stimulation in Raw264.7 cells, and the expression of IL-1β and IL-18 at the colitis site in vivo." (PMID 36843930, 2023). "Our results suggest that the use of AO treatment, especially the optimal concentration of ATR, confers therapeutic advantages in the context of colitis by prohibiting the expression of proinflammatory cytokines such as IL-6 and TNF-α." (PMID 37959758, 2023). "The expression of IL-6, the major cytokine produced in the colitis, was below the detectable level in the control and DSS-EV mice, while it was abundant in the DSS-treated mice." (PMID 37966243, 2023).
colitis (continued). "We also found that NFκB signaling components were elevated in the model mice, as well as the protein expression of JAK2, p-Stat3/Stat3, and IL-6, suggesting increased colitis in the model group." (PMID 38004214, 2023). "ALA-rich sage oil ameliorates colitis by down-regulating pro-inflammatory genes, including IL-6, COX2, TNFα, IL-8, and iNOS." (PMID 37868958, 2023). "The closely correlated pro-inflammatory cytokines in lipid metabolism are TNF-a, IL-17a, IL-4, and IL-6, and these molecules promote colitis progression." (PMID 37569708, 2023). "Dexamethasone (p < .001, F.C: −11.49) and QA at 10 (p < .05, F.C: −2.12), 30 (p < .001, F.C: −6.75), 60 (p < .001, F.C: −12.19), and 100 (p < .001, F.C: −18.51) mg/kg attenuated the IL‐6 expression in comparison to the colitis values." (PMID 37647443, 2023). "A previous study showed that magnolol exerts anti-inflammatory effects when reducing the serum levels of IL-17 and IL-6 in a rat colitis model." (PMID 37214308, 2023). "Accumulating evidence showed IL-6 and IL-17 as the primary cytokines in experimental colitis, and the average numbers of IL-6 and IL-17 were significantly increased in UC patients." (PMID 36832826, 2023). "Ligliptin activated the AMPK-SIRT1-PGC-1α pathway and inhibited the JAK2/STAT3 signaling pathway, downregulated TNF-α, IL-6 and NF-κB p65, and upregulated the anti-inflammatory cytokine IL-10, reducing the severity of colitis." (PMID 37483618, 2023). "The activation of LXRs in a mouse colitis model can suppress the expression of inflammatory factors such as IL-1β, IL-6, IL-17A, TNFα, and chemokines such as CXCL1/KC, CXCL2/MIP2, CXCL8/IL-8, CCL2/MCP1 and CXCL10 in the colon tissue." (PMID 37720208, 2023). "In this study, high concentrations of colonic TNF-α, IL-6, and IL-1β were observed in mice with colitis, which was in agreement with a previous study." (PMID 37762155, 2023). "In the DSS colitis model of colitis, Ufbp1fl/fl/VillinCre mice show increased pro‐inflammatory cytokine (IL‐6, IL‐1β) production and are sensitive to tissue damage." (PMID 36680403, 2023). "Transcription of IL-6 cytokine increased by 11.7-folds, and IL-17A increased by 6.3-folds in the colitis tissues of ICB-treated patients with irEC." (PMID 37605139, 2023). "In accordance with the preceding investigations, this study revealed increased levels of TNF-α immunostaining after AA-colitis induction and augmented levels of IL-6." (PMID 37895902, 2023). "In the present study, PHI efficaciously suppressed the expressions of TNF-α, IL-1β, and IL-6 in colitis mice." (PMID 36768559, 2023). "Alleviated the disruption of Intestinal barrier function, alleviated colitis symptoms, Inhibiting the Production of IL-6, TNF-R1, TNF-R2, and TNF-α." (PMID 37485519, 2023). "A previous study in mice has shown that blocking IL-17 leads to worsening of colitis by increasing tumor necrosis factor-α, interferon-γ, IL-6, and cytokines that promote the inflammatory response." (PMID 37033665, 2023). "Supplementation with dihydroquercetin significantly reversed DSS-induced colitis in mice via down-regulating levels of IL-1β, IL-6, TNF-α, and up-regulating serum IL-10, colonic ZO-1, occludin, and Lactobacillus levels." (PMID 37298531, 2023). "NETs can activate macrophages to release cytokines such as IL-1β, TNF-α, IL-6, induce the activation of platelets and intestinal epithelial cells, promoting colitis and thrombosis." (PMID 37720208, 2023). "Compared with WT mice, S1PP2−/− mice had higher intestinal epithelial barrier integrity (manifested as increased expression of E-cadherin) and lower levels of TNF, IL-1β and IL-6 in intestinal tissue in the DSS-induced colitis mouse model." (PMID 37560160, 2023). "The maximum inflammatory response was found in the DSS-induced colitis model, as shown by higher detected levels (p < 0.05) of IL-6, TNF-α, IFN-γ, and IL-10 cytokines." (PMID 35884960, 2022).
colitis (continued). "Further studies uncovered that PYY 3–36 treatment reduced the levels of colon myeloperoxidase (MPO) and both colonic and systemic TNF-α and IL-6 observed in murine colitis." (PMID 35443853, 2022). "Higher levels of pro-inflammatory cytokines including TNF-α, IL-1β, and IL-6 and lower levels of anti-inflammatory cytokine IL-10 were found in colitis mice when compared with the control group." (PMID 35911761, 2022). "The acute inflammatory response that occurs in mice with DDS-induced colitis is at least partially related to the overexpression of the inflammatory cytokines IL-1β, IL-6, and TNF-α." (PMID 36431883, 2022). "A few reports have indicated the importance of IL-6 in the pathophysiology of experimental colitis and human IBD." (PMID 35001008, 2022). "Opposite to TNF, there was a reduction in IL-6 levels in the hippocampus of vehicle-treated colitis mice." (PMID 35295931, 2022). "In contrast, the levels of TNF-α, IL-6, and IL-1β were increased considerably, indicating that colon inflammation was induced in mice after DSS treatment." (PMID 36359970, 2022). "Inconsistent with the results of our study, two studies showed Clostridium butyricum reduced colitis-associated CRC on AOM/DSS murine models and decreased proinflammatory cytokines TNF-α, IL-6, and COX-2, and increased anti-inflammatory cytokine IL-10." (PMID 36077084, 2022). "Lactobacillus acidophilus treatment can also alleviate the severity of DSS-induced colitis and inhibit pro-inflammatory cytokines in the colon, such as IL-1β、 IL-6、IL-17, and TNF-α." (PMID 36189293, 2022). "This reduction in CXCL12 expression subsequently inhibits macrophage functions, including migration to the tumour site and secretion of the proinflammatory cytokine IL‐6, to suppress colitis and tumorigenesis." (PMID 35363937, 2022). "Meanwhile, the levels of inflammatory factors TNF-α, IL-1β, and IL-6 were upregulated in DSS-induced colitis mice." (PMID 35630568, 2022). "In short, BBR motivated cell advancement, and alleviated intestinal barrier damage in IL-6-induced colitis model in vitro." (PMID 35259053, 2022). "It was remarkable that rats that suffered from DSS-induced colitis had the highest expression levels of pro-inflammatory cytokines IL-6, IL-1β and TNF-α and anti-inflammatory IL-10 levels." (PMID 35745756, 2022). "Follow up studies showed that obeticholic acid (OCA), a semi-synthetic bile acid used as medication and potent FXR agonist, prevented DC migration from the spleen to the colon in response to DSS-colitis with an increase in plasma IL-10 levels and IL-6 levels." (PMID 36569849, 2022). "Network of cytokines including IL-1β, TNF-α, IL-6, IL-10, IFN-γ, and IL-18, have been reported to regulate mucosal inflammation in colitis, and IL-6, TNF-α are viewed as therapeutic targets in IBD." (PMID 35330829, 2022). "It has been shown that IL-6 plays an important role in colitis in mice and accordingly, inhibition of IL-6 secretion plays a key role in the treatment of intestinal inflammation." (PMID 36142699, 2022). "Meanwhile, TNF-α, IL-6, and IL-1, proinflammatory cytokines, are crucial in the development of colitis." (PMID 36500439, 2022). "Ginseng polysaccharides were demonstrated to alleviate colitis symptoms in rats, accompanied by the downregulation of inflammatory cytokines (IL-1β, IL-2, IL-6, and IL-17)." (PMID 35745651, 2022). "IL-6 concentration is the lowest in both group of animals fed a HFD with colitis and IAP administration and it is significantly lower than in the group with only access to SW (p < 0.05)." (PMID 35328382, 2022). "Overexpression of NF-κB induces the hyperactivation of inflammatory response and promotes the release of proinflammatory cytokines (containing TNF-α, IL-6, and IL-1β), even facilitating the occurrence of colitis." (PMID 35681301, 2022).